EGFR (epidermal growth factor receptor)
Diseases named in the same sentence as EGFR in open-access papers (continued):
Sharing a sentence is not in itself a finding about the gene and the disease.
cancer (continued). "More than 600 types of epidermal growth factor receptor (EGFR) mutations are described in the Catalogue of Somatic Mutations in Cancer (COSMIC)." (PMID 36042660, 2022). "GSEA analysis and SPRY1 showed a positive correlation to genes associated with EGFR signaling, and cancer proliferation." (PMID 35910677, 2022). "EGFR alterations in cancer include mutations—for instance in non‐small cell lung cancer (NSCLC)—managed with tyrosine kinase inhibitors (TKIs), or overexpression (e.g., in colorectal cancer), often managed with monoclonal antibodies (mAbs)." (PMID 35212471, 2022). "Several clinical and preclinical studies are being carried out to better understand the mechanisms of resistance to 3rd G EGFR-TKIs and have revealed various genetic aberrations associated with molecular heterogeneity of cancer cells." (PMID 35463360, 2022). "Previous research has shown that EGFR-TKIs are a suitable treatment modality that is beneficial for cancers (with mutations in the EGFR gene)." (PMID 36793341, 2022). "These anti-cancer effects are associated with the downregulation of the EGFR signalling pathway and activation of caspase-7, PARP cleavage, and DNA/RNA damage." (PMID 35120511, 2022). "The gene expression of proapoptotic (Bax and Caspase-3) and cancer-associated genes which promote cell survival (Bcl-2, Survivin, EGFR, and VEGF) were analyzed in RT-PCR." (PMID 35578215, 2022). "Mutations and overexpression of EGFR in various human cancers are frequent; hence, EGFR targets several current cancer therapies." (PMID 36438839, 2022). "The favourable outcomes reported for both late stage and early stage cancer from tyrosine kinase inhibitors (TKIs) targeted for EGFR mutated NSCLC highlight the importance of summarizing the frequency of such mutations among populations." (PMID 36661661, 2022). "We find EGFR-mut cancers have a significantly lower mutational burden than the other subtypes and conserve 16 genes related to DNA repair compared to 1 and 3 in NEK and KRAS-mut subtypes, respectively." (PMID 36612014, 2022). "Two patients with locally advanced cancer disease, harboring EGFR mutation received concurrent chemoradiation therapy according to the current standard of care." (PMID 35108331, 2022). "An extensively studied biomarker, EGFR is one of the most implicated genes in carcinogenesis due to its frequent overexpression and mutations in multiple cancers." (PMID 35409179, 2022). "Several studies showed that DTPs in EGFR-mutated models treated with EGFR-TKI express cancer stem cell markers." (PMID 35681591, 2022). "Overexpression of EGFR is implicated in the pathogenesis of many human cancers, including NSCLC and has been known to correlate with poor prognosis." (PMID 35932303, 2022). "Preclinical studies indicated that EGFR mutations lead to cancer immune escape through the PD-1/PD-L1 pathway." (PMID 35742933, 2022). "EGFR has been implicated in multiple human cancers, including carcinomas of the head and neck and breast." (PMID 35569509, 2022). "High EGFR expression is associated with an increased risk of metastasis and drug resistance, and the inhibition of EGFR leads to a reduction in cancer migration and angiogenesis and an increase in drug sensitivity in cancers." (PMID 35723316, 2022). "As clinical targeted therapy, EGFR kinase inhibitors are effective only when the cancer cells contain specific EGFR-activating mutations that alter downstream signaling." (PMID 35840984, 2022).
cancer (continued). "EGFR gene mutation has a certain correlation with cancer treatment, and many scholars have also made achievements in this field." (PMID 36685887, 2022). "The mutation rate of the classical cancer-related gene EGFR was substantially higher in C3 than in C1 and C2." (PMID 35620271, 2022). "Erlotinib, is an EGFR tyrosine kinase inhibitor that prevents intracellular phosphorylation of EGFR in cancer cells, preventing downstream signaling and causing cancer cell death." (PMID 36199696, 2022). "In low nanomolar concentrations, the NB-IR700DX conjugates cause cell death in EGFR-overexpressing cancer cells, whereas IR700DX alone or the Nb–PS conjugates in dark conditions does not induce toxicity." (PMID 35213974, 2022). "EGFR mutations and overexpression played a role in cancer cell proliferation, metastasis, chemotherapy resistance and also metabolism in NSCLC." (PMID 35805016, 2022). "These activating EGFR mutations lead to alterations in ligand-dependent cellular signaling promoting cell survival, proliferation and continuous replication of cancer cells." (PMID 35884398, 2022). "Epidermal growth factor receptor (EGFR) is overexpressed or mutated in many types of cancers, including GBM, and correlates with poor clinical prognosis." (PMID 36435833, 2022). "New diagnoses accounted for 28 of 92 (30%) patients with EGFR-mutated cancers with 82 (89%) being at stage IV and 89 (97%) being at stage III or IV." (PMID 35202431, 2022). "EGFR wild‐type overexpression has been linked to disease progression and dismal prognosis in various cancers." (PMID 35212471, 2022). "A cancer-associated mutation in the Ack1 UBA domain increases the stability of EGFR and leads to prolonged Ras/Raf/MAPK activation." (PMID 36334623, 2022). "Nevertheless, NSCLC cancer cells, especially those with EGFR mutations, target and infiltrate the brain frequently." (PMID 36457515, 2022). "EGFR mutations in the tyrosine kinase domain increase EGFR kinase activity and signs of tumorigenesis such as cancer cell proliferation, migration, invasion, and angiogenesis." (PMID 36429891, 2022). "For example, cancers harboring exon 20 insertions, which represent approximately 4–12% of EGFR mutations, are generally insensitive to first- and second-generation EGFR-TKIs." (PMID 35626123, 2022). "The univariate analysis revealed that age, sex, smoking, drinking, EGFR mutation, different cancer stage, histological type, and operation were significantly associated with all-cause mortality." (PMID 36233811, 2022). "A large fraction of human cancers displays elevated EGFR and kinase activity through overexpression and/or mutations." (PMID 36221123, 2022). "EGFR mutant targeted therapy targets the main oncogene linked with tumorigenesis and is important for cancer maintenance." (PMID 35402265, 2022). "In the latest studies, compound 1 selectively inhibited the growth of NSCLC cells with EGFR mutation, thus demonstrating its excellent anti-cancer activity." (PMID 35736208, 2022). "Specifically, the EGF receptor (EGFR), a transmembrane protein tyrosine kinase, is frequently mutated and overexpressed in various types of human cancers, including breast cancers." (PMID 35122791, 2022). "A different target is the deletion-mutation form of EGFR (known as EGFRvIII), expressed in a wide range of cancer tissues, including HCC tissues." (PMID 35814023, 2022). "Prior to surgery, 101 patients had undergone a diagnostic biopsy; EGFR mutational analysis was available in 56 (55%) patients and 12 patients (21%) had a cancer harboring an EGFR mutation." (PMID 35847912, 2022). "The challenge of overcoming intrinsic and acquired resistance in primary and recurrent cancer mediated by EGFR mutations is thus driving the search for alternative strategies in the design of new therapeutic agents." (PMID 35840984, 2022).
cancer (continued). "In a nutshell, the combination therapy of TKIs and ICIs is in too early a stage, and further studies and assessments are required to treat cancer patients with EGFR overexpression or mutations." (PMID 36438839, 2022). "In one study, EV-producing cells were transfected with a vector encoding for anti-EGFR nanobodies fused to glycosylphosphatidylinositol (GPI) peptides to target cancer cells." (PMID 36290464, 2022). "EGFR, which is frequently mutated and/or overexpressed in different cancers, has prognostic significance and is the target of multiple cancer therapies." (PMID 36471329, 2022). "By this criterion, EGFR-mut cancers, consistent with the cohort’s overall decreased mutation rate, have only 10 gene mutations under directional selection compared to 153 and 205 for KRAS-mut and NEK, respectively." (PMID 36612014, 2022). "Because there is a clear association between EGFR and NLRP3 in cancer cells, we examined EGFR-associated NLRP3 inflammasome activation in astrocytes in this study." (PMID 36341365, 2022). "EGFR mutation and/or overexpression has been observed in several human cancers, and EGFR-targeted therapy has become a routine part of the treatment of several cancers." (PMID 35884975, 2022). "Using this method, researchers found that cancer‐related EGFR‐L858R (EGFR, epidermal growth factor receptor) and BRAF‐V600E mutations with allelic fractions as low as 0.1% can be detected in cell‐free DNA fragments." (PMID 35845351, 2022). "Some studies have demonstrated that activation of wild-type or mutated EGFR cancer cells stimulates SCAMP3 phosphorylation, promoting the interaction of both proteins." (PMID 35681787, 2022). "Numerous reports on the association with radiation have been made for EGFR, which is a receptor of tyrosine kinase involved in cell survival/growth signaling that is overexpressed in several cancers." (PMID 36139779, 2022). "By dissecting diverse cell types comprising the TME, we identified a novel subset of cancer-associated fibroblast, which showed enriched epidermal growth factor receptor (EGFR)-related transcripts including early growth response 1 and 2 (EGR1 and EGR2)." (PMID 35464471, 2022). "NGS has successfully guided the clinical choice of targeted therapies and immunotherapy for various cancers through the identification of several actionable variants, EGFR, HER2, and PARP, achieving significant clinical benefits in multiple cancer types." (PMID 36204371, 2022). "For example, 8 collagen (COL) family members are either conserved or highly mutated in EGFR-mut cancers." (PMID 36612014, 2022). "Specifically, overactivation of EGFR signaling, caused by mutations in EGFR itself or in genes encoding downstream signal transducers, is known to contribute to the formation and progression of various cancer types in humans." (PMID 34982813, 2022). "The EGFR gene regulates many physiological processes and induces important mechanisms associated with cancer." (PMID 36291859, 2022). "Amplification of the EGFR gene and frequent mutations in the EGFR tyrosine kinase domain have recently been demonstrated in cancer patients." (PMID 35027542, 2022). "As an example of detecting targetable mutations in cancer patients, the Cobas EGFR mutation test v2 (Roche) aims to detect by PCR from plasma in less than 4 h specific and actionable mutations in the EGFR gene exons 18-21." (PMID 39697490, 2022). "As a tyrosine kinase inhibitor (TKI), afatinib received FDA approval to be used in targeted therapy for patients with EGFR mutation-positive cancers." (PMID 35163685, 2022). "The third-generation inhibitor Osimertinib (OSI, Tagrisso®, AstraZeneca UK Limited, Chesire, England, approved in 2017) has been specifically developed for cancers driven by the T790M EGFR mutation." (PMID 36009762, 2022).
cancer (continued). "The latest NSCLC guideline 2021 V2 edition issued by the national comprehensive cancer network (NCCN) indicated that genes associated with targeted therapy of NSCLC include EGFR, KRAS, ALK, ROS1, MET, BRAF, RET, and NTRK." (PMID 35227278, 2022). "Research on EGFR-mutant cancer cell lines revealed that gefitinib resistance was associated with an oncogenic mutation in phosphatidylinositol-4,5-bisphosphate 3-kinase catalytic subunit alpha (PIK3CA)." (PMID 35814435, 2022). "These RAS mutations drive cancer proliferation through epidermal growth factor receptor (EGFR)-independent activation of the mitogen-activated protein kinase (MAPK) signaling pathway." (PMID 35804994, 2022). "zDHHC20 has been implicated in the development of cancers resistant to epidermal growth factor receptor (EGFR) inhibitor therapies." (PMID 36087837, 2022). "Conversely, somatic EGFR mutations drive epithelial cell-derived tumors such as lung and other types of cancer." (PMID 35840668, 2022). "In HNSCC, EGF family ligand expression, including EREG, associates with better responses to the EGFR inhibitor cetuximab, reflecting the increased dependence on EGFR signaling in these cancers." (PMID 36506869, 2022). "Further, it would be interesting to explore the potential of 6b in the future, besides serving as a lead for structural modifications, in a gefitinib-resistant H1975-induced xenograft model to understand its impact in EGFR mutated cancers." (PMID 36080307, 2022). "Although inappropriate activation of EGFR in cancer is mainly caused by amplification and point mutation of genomic sites, transcription upregulation or ligand overproduction are also induced by autocrine/paracrine mechanisms." (PMID 36060002, 2022). "Compared with adjacent normal tissue, Beclin 1 expression was elevated in the cancer tissue significantly; assessments of EGFR and ALK mutations showed that out of the 480 patients, 233 (48.5%) and 75 (12.6%) patients had EGFR and ALK mutations." (PMID 36401689, 2022). "Target SelectorTM EGFR Mutation Test Kit detects EGFR mutations in DNA derived from plasma or FFPE tissue sections to give insight into cancer characteristics and provide biomarker status of tumors, such as NSCLC." (PMID 35735625, 2022). "In HNC, ER and epidermal growth factor receptor (EGFR) are associated and are involved in cancer development and disease progression." (PMID 36233715, 2022). "Epidermal growth factor receptor (EGFR) driver mutation cancers represent a distinct subset of non-small-cell lung cancer (NSCLC) with broad molecular and clinical heterogeneity." (PMID 36110964, 2022). "Screening of the training set revealed that six items (gender, age, invasive degree, cancer density, vacuole sign, and smoking history) were all independent predictors for EGFR mutation." (PMID 35186727, 2022). "HER3 has been shown to play a critical role in EGFR- and HER2-dependent cancers, including cancer cells harboring an EGFR mutation or amplification of the ERBB2 gene." (PMID 35249128, 2022). "We also tested the effects of RhoA in the H1975 cells, which express EGFR L858R and T790M mutations and form metastasis in mice even when osimertinib treatment is started 2 days after cancer cell injection (black and gray curves)." (PMID 36509758, 2022). "Previous studies have reported that EGFR signaling mediates cancer-stroma crosstalk and is associated with metastasis and recurrence." (PMID 36418422, 2022). "EGFR mutation is one of the most frequently observed mutations in Asian patients with cancer, and is diagnosed in approximately 50% of the patients." (PMID 35745617, 2022). "One potential explanation for the lack of complete and durable responses is that oncogene-driven cancers with activating mutations of EGFR often harbor additional co-occurring genetic alterations." (PMID 35579943, 2022). "Recently, MEK/ERK pathway inhibitors have been proposed as a new strategy for cancers with EGFR, RAS, and RAF mutations." (PMID 35614034, 2022).
cancer (continued). "This study addresses an emerging and important question: What, if any, is the impact of co-occurring genetic alterations in cancers harboring a canonical primary driver mutation, such as mutant EGFR?" (PMID 35579943, 2022). "For instance, while one study reported that EGFR mutations occur in 9% of cancer patients, another study conducted on the Asian population found the mutation frequency of EGFR was 20%." (PMID 36447228, 2022). "The ERK pathway is the major target pathway for drugs such as CET, used in the treatment of EGFR-mutated cancer." (PMID 35277058, 2022). "Mechanically, because of molecular structural similarity with EGF, the association between SPINK1 and EGFR has been studied in many cancers." (PMID 36053457, 2022). "EGFR is an ideal candidate for cancer target as it is often overexpressed in cancer cells and the overexpression is associated with advanced disease and poor prognosis." (PMID 36678740, 2022). "These EGFR-activating mutations, also called EGFR-sensitizing mutations, make cancer cells become dependent upon the EGFR signaling pathway and stimulate cancer cell proliferation, angiogenesis, and the evasion of apoptosis by activating downstream effectors." (PMID 35408753, 2022). "EGRFvIII, a mutated Epidermal Growth Factor Receptor (EGFR) from an in-frame deletion of exons 2 to 7, is the most common variant of this receptor in cancers." (PMID 35265074, 2022). "Second, we have clarified before that the TGF-β/Smad3 pathway, which is associated with the development of some human cancers, can be activated via persistent transactivation of EGFR after ARAP1 regulation." (PMID 35291911, 2022). "The physiological role of EGFR is to regulate epithelial cell function, and mutated EGFR is aberrantly expressed to trigger cancer, and such mutations are found in more than half of Asian NSCLC patients." (PMID 36313314, 2022). "The G796R mutation has been detected in cancer patients who received treatment with a third-generation EGFR-TKI." (PMID 35840984, 2022). "Since TGF binds to EGFR and causes tyrosine phosphorylation of the receptor, it is plausible to consider that both substances influence cancer signaling pathways." (PMID 36430763, 2022). "It was found that, in addition to acquiring drug-resistant mutations, the continued activation and transmission of EGFR signals provided survival advantages for cancer cells." (PMID 35706930, 2022). "In cancer, constitutive activation of EGFR is associated with cell proliferation, survival and migration." (PMID 35337159, 2022). "For example, the type III variant EGFR (EGFRvIII) was considered as an ideal target for its aberrant expression on the cell surface of cancer cells." (PMID 35372044, 2022). "In cancer, abnormal activation of EGFR and HER2 can be induced by gene amplification, point mutation, deletion, and autocrine ligand–receptor stimulation." (PMID 35903358, 2022). "Studies have shown that epigenetic disorders can make cancer patients susceptible to acquired resistance to EGFR-TKIs." (PMID 35840984, 2022). "Our data showed that detection of EGFR mutations failed in CTCs of many patients when they were receiving anti-cancer therapy (at the third-month timepoint)." (PMID 36142574, 2022). "EGFR mutations are responsible for activation of constitutive ligand-independent receptor and regulation of downstream signaling pathways, promoting cancer proliferation and cell survival." (PMID 36619616, 2022). "The lower detection levels for BRAF and EGFR mutations on the Idylla system with the cBioPortal for Cancer Genomics dataset can be attributed to the fact that most of the identified variants are rare and/or non-pathogenic." (PMID 35627184, 2022). "Various cancer-promoting pathways have been linked to endothelin receptor activation, including β catenin and EGFR signaling." (PMID 35625966, 2022).